DKK1 (dickkopf Wnt signaling pathway inhibitor 1)
Diseases named in the same sentence as DKK1 in open-access papers (continued):
Sharing a sentence is not in itself a finding about the gene and the disease.
chondrosarcoma (5 papers, 2014 to 2023). A malignant cartilaginous matrix-producing mesenchymal neoplasm arising from the bone and soft tissue. "In conclusion, we have identified that elevated DKK1 levels associated with nuclear β-catenin accumulation play a role in the pathogenesis of chondrosarcoma, and can indicate poor prognosis of patients with chondrosarcoma." (PMID 25144498, 2014). "Our observations have implicated DKK1 and β-catenin in the pathogenesis and prognosis of chondrosarcoma." (PMID 25144498, 2014). "Association among DKK1 level, β-catenin accumulation and clinicopathological factors in 63 patients with chondrosarcomas." (PMID 25144498, 2014). "Elevated DKK1 levels associated with β-catenin accumulation play a crucial role in chondrosarcoma." (PMID 25144498, 2014). "Previously, we have presented the evidence that DKK1 levels were remarkably elevated in chondrosarcoma specimens and DKK1 suppressed canonical Wnt/β-catenin signaling in human chondrosarcoma SW1353 cells." (PMID 25999350, 2015). "No reports have been documented regarding as the relationship between DKK1 levels and β-catenin accumulation in chondrosarcoma." (PMID 25144498, 2014). "Our findings suggest that elevated levels of DKK1 and β-catenin play a role in the pathogenesis of chondrosarcoma, and DKK1 can be recognized as an independent factor to predict the prognosis of chondrosarcoma patients." (PMID 25144498, 2014). "Through further understanding of the role of Wnt/β-catenin pathway activation, DKK1 and β-catenin would be a potential therapeutic target for chondrosarcoma management." (PMID 25144498, 2014). "High DKK1 level and positive β-catenin accumulation in chondrosarcoma specimens were 58.7% and 53.9%, respectively." (PMID 25144498, 2014). "In particular, multivariate analysis had revealed that among the clinicopathological factors, DKK1 was identified as an independent prognostic factor for the overall survival in 63 patients with chondrosarcoma." (PMID 25144498, 2014). "Accordingly, elevated levels of DKK1 in chondrosarcoma would be consistent with a role for DKK1 in promoting development and aggressiveness of chondrosarcoma in vivo." (PMID 25144498, 2014). "The positive signal of DKK1 was preferentially identified at the cytoplasm, and high DKK1 expression was 58.9% (37/63) in chondrosarcomas samples as compared with 23.5% (4/17) in benign cartilage tumors (P = 0.014)." (PMID 25144498, 2014). "In this study, elevated level of DKK1 positively correlated with β-catenin accumulation in chondrosarcoma tissues (P = 0.000)." (PMID 25144498, 2014). "To our knowledge, for the first time, we have explored the potential prognostic significance of DKK1 in chondrosarcoma." (PMID 25144498, 2014). "To explore the expression profiles of DKK1 and β-catenin in human cartilage tumors, we performed immunochemistry analysis for 63 patients with chondrosarcoma and 17 patients with benign cartilage tumors." (PMID 25144498, 2014). "DKK1 has been proved to be an independently valuable factor in predicting the prognosis of patients with chondrosarcoma." (PMID 25144498, 2014). "This study was designed to investigate the expression profiles of DKK1 and β-catenin, and to clarify their clinical values in chondrosarcoma." (PMID 25144498, 2014). "Moreover, malignant chondrosarcoma cells exhibited higher DKK1 levels, mainly in the cytoplasm, whereas benign cartilage tumors showed lower DKK1 levels." (PMID 25144498, 2014). "Elevated levels of DKK1 significantly correlated with nuclear β-catenin accumulation could be involved in the development of chondrosarcoma, and DKK1 can be identified as an independent prognostic factor for the overall survival in chondrosarcoma." (PMID 25144498, 2014). "Furthermore, DKK1 level and β-catenin accumulation had significant impacts on the prognosis of chondrosarcoma patients." (PMID 25144498, 2014). "DKK1 can serve as a novel predictor of poor prognosis in patients with chondrosarcoma." (PMID 25144498, 2014).
chondrosarcoma (continued). "Thus, it is pertinent at this point to determine whether DKK1 level correlates with β-catenin accumulation in chondrosarcoma." (PMID 25144498, 2014). "The Dickkopf WNT signaling pathway inhibitor 1 (DDK1) gene, an antagonist of canonical WNT/β-catenin signaling, and β-catenin were progressively overexpressed in chondrosarcoma tissues with increasing histological grade and correlated with poor prognosis." (PMID 32566253, 2020). "Thus, to determine whether DKK1 level and β-catenin accumulation could be predictive for the prognosis of 63 cases of chondrosarcoma patients, the Kaplan-Meier analysis was performed, and showed that DKK1 level had a significant effect on the overall survival (P = 0.015)." (PMID 25144498, 2014). "Both DKK1 and β-catenin levels were remarkably elevated in chondrosarcoma compared with the corresponding non-tumor tissues." (PMID 25144498, 2014). "To our knowledge, we present the first evidence that the mRNA and protein levels of DKK1 were significantly elevated in fresh chondrosarcoma tissues compared with the corresponding non-tumor tissues." (PMID 25144498, 2014). "The mRNA and protein levels of DKK1 and β-catenin in fresh chondrosarcoma and the corresponding non-tumor tissues were analyzed by Real-time PCR and Western blot, respectively." (PMID 25144498, 2014). "However, the clinical significance of DKK1 and β-catenin in chondrosarcoma has not been well characterized." (PMID 25144498, 2014). "However, the biological role of DKK1 and β-catenin involved in chondrosarcoma has not been sufficiently investigated." (PMID 25144498, 2014). "To identify whether the expression levels of DKK1 and β-catenin are involved in the pathogenesis of chondrosarcoma, we measured the mRNA and protein levels of DKK1 and β-catenin in chondrosarcomas and the corresponding non-tumor tissues." (PMID 25144498, 2014).
colorectal tumors (5 papers, 2006 to 2024). "This parallels previous data for WIF-1 and DKK-1, and infers that colorectal tumours should express high levels of all three classes of Wnt antagonists as a result of the β-catenin stabilising mutations normally present." (PMID 16523202, 2006). "Furthermore, as DKK1 is expressed in colorectal tumor tissues since early tumor developmental stages, we measured serum DKK1 in patients with colorectal tumors to evaluate its usefulness as a biomarker." (PMID 38334454, 2024). "In conclusion, during the development of colorectal tumors, fibroblasts express DKK1 from the early stage of tumorigenesis and may function in a tumor‐suppressive manner." (PMID 38334454, 2024). "Furthermore, we measured serum DKK1 in patients with colorectal tumors to evaluated its usefulness as biomarker, The analysis revealed significantly higher serum DKK1 levels in the advanced cancer patient group than in the control group; th AUC was 0.78." (PMID 38334454, 2024). "DKK1 is a direct Wnt target gene with increased expression in many cancers, however, here DKK1 was chosen particularly because its expression had previously been reported to be reduced in colorectal tumor." (PMID 32403323, 2020).
coronary atherosclerosis (5 papers, 2013 to 2024). Atherosclerosis of the coronary vasculature. "Increased level of DKK-1 may imply more serious coronary atherosclerosis and high-risk or vulnerable coronary plaque in patients with ACS." (PMID 23359112, 2013). "The study aimed to assess serum RANKL:OPG ratio, Dkk-1 and deposition of calcium in aortic valve in relation to the presence of concomitant coronary atherosclerosis in patients with symptomatic calcified aortic stenosis (CAS)." (PMID 25889943, 2015). "Circulating Dkk-1 and calcium deposition in aortic valve differ significantly in relation to the presence of coronary atherosclerosis in patients with symptomatic CAS." (PMID 25889943, 2015). "The study documented significant differences in serum Dkk-1 signaling and deposition of calcium in aortic valves in relation to the presence of concomitant coronary atherosclerosis in patients with symptomatic CAS." (PMID 25889943, 2015). "The study also suggested that DKK1 plasma levels could serve as a prognostic predictor for the severity and stability of coronary atherosclerosis." (PMID 38175715, 2024). "Furthermore, DKK1 plasma levels could serve as a prognostic predictor of the severity and stability of coronary atherosclerosis." (PMID 38175715, 2024). "Patients with CAS and normal coronary angiography, with significantly higher Dkk-1 signaling and significantly higher load of calcium were symptomatic at significantly younger age in comparison to patients with CAS and significant coronary atherosclerosis." (PMID 25889943, 2015). "Presence of coronary atherosclerosis was related to significantly (p = 0.007) higher OPG and to significantly (p = 0.004) lower Dkk-1." (PMID 25889943, 2015). "Presence of coronary atherosclerosis was related to significantly higher OPG and to significantly lower Dkk-1 in comparison to presence of normal coronary arteries in patients with CAS." (PMID 25889943, 2015). "Conversely, multivariable regression underscored the significance of difference in Dkk-1 signaling in relation to the presence/absence of concomitant coronary atherosclerosis in patients with CAS (pafter adjustement = 0.020)." (PMID 25889943, 2015). "Therefore, the study was designed to asses serum RANKL/OPG ratio, Dkk-1 signaling and deposition of calcium in aortic valve in patients with symptomatic CAS in relation to the presence of concomitant coronary atherosclerosis." (PMID 25889943, 2015). "Therefore we designed a study which aimed to asses serum RANKL/OPG ratio, Dkk-1 signaling and deposition of calcium in aortic valve in patients with symptomatic CAS in relation to the presence of concomitant coronary atherosclerosis." (PMID 25889943, 2015). "Dkk-1 and deposition of calcium in aortic valve differ significantly in relation to the presence/absence of coronary atherosclerosis in patients with symptomatic CAS." (PMID 25889943, 2015).
gastric adenocarcinoma (5 papers, 2021 to 2025). "DKK1 (Dickkopf‐1) is a molecule that is overexpressed in gastric adenocarcinoma and affects cell proliferation and metastasis by inhibiting the activation of the Wnt signalling pathway." (PMID 38752750, 2024). "Univariate and multivariate Cox analyses of DKK1 expression with overall survival (OS) among stomach adenocarcinoma (STAD) patients." (PMID 34899842, 2021). "In summary, molecules such as DKK1, GHRL, STC1, NRP1 and ITGAV play important roles in the development and prognosis of gastric adenocarcinoma." (PMID 38752750, 2024). "Activation of MMP-7 by DKK1 and Wnt/β-catenin pathway is known to induce T-DM1 or ado-trastuzumab resistance, and lead to poor prognosis in gastric adenocarcinoma." (PMID 33918254, 2021).
head and neck squamous cell carcinoma (5 papers, 2020 to 2024). A squamous cell carcinoma that arises from any of the following anatomic sites: lip and oral cavity, nasal cavity, paranasal sinuses, pharynx, larynx, and salivary glands. "DKK1 is an important factor of the immunosuppressive tumor microenvironment in head and neck squamous cell carcinoma and parcticipates in the development of resistance to radiotherapy and immunotherapy." (PMID 38609887, 2024). "For example, a study investigating lncRNA expression profile in 502 head and neck squamous cell carcinoma (HNSCC) patients identified a significantly elevated level of lncRNA activating regulator of DKK1 (LNCAROD) associated with tumor stage and reduced overall survival." (PMID 34065036, 2021). "METTL3/14 enhance the migration of head and neck squamous cell carcinoma (HNSCC) by upregulating lncRNA activating regulator of DKK1 (LNCAROD)." (PMID 32767982, 2020). "For example, a study developed a prognostic model based on four cellular senescence-related genes (BAK1, DKK1, CDKN2A, and MIF) to predict the survival rate of individuals with head and neck squamous cell carcinoma." (PMID 37580647, 2023).
Hyperglycemia (5 papers, 2011 to 2024). An increased concentration of glucose in the blood. "Hyperglycemia increases the mesangial cell expression of DKK1, the Kremen-2 receptor, transforming growth factor-β (TGF-β), and fibrotic factors, thus ultimately escalating to damage to the glomerular filtration barrier, leading to DKD." (PMID 36012674, 2022). "Pre-miR-29a treatment in diabetic mice significantly restored the levels of β-catenin, and prevented upregulation of profibrotic factors, including TGF-β1, fibronectin, and DKK1, induced by hyperglycemia." (PMID 27460630, 2016). "Independently, DKK-1 was also shown to promote hyperglycaemia-induced mesangial matrix accumulation and renal dysfunction in rat mesangial cells." (PMID 21876774, 2011). "Additionally, the imbalanced expression of DKK1 and nuclear β-catenin promotes hyperglycemia-mediated cell apoptosis and the synthesis of the fibrotic matrix in DKD." (PMID 36012674, 2022). "At 1 h post-hypoglycemia, the changes in ANGPT1, DKK1, and BOC had resolved, with no additional protein biomarker changes despite rebound hyperglycemia from 1.8 ± 0.1 to 12.2 ± 2.0 mmol/L." (PMID 38927344, 2024).
ischemia (5 papers, 2009 to 2025). A hypoperfusion of the BLOOD through an organ or tissue caused by a PATHOLOGIC CONSTRICTION or obstruction of its BLOOD VESSELS, or an absence of BLOOD CIRCULATION. "When contrasted with DKK1 or Lucentis, catalpol exhibited similar protective effects against retinal ischemia via significantly (p < 0.05) blunting the ischemia-induced overexpression of β-catenin, VEGF, or angiopoietin-2." (PMID 40362263, 2025). "Similarly, DKK-1 also reduced the ischemia-induced retinal neovascularization, the VEGF expression." (PMID 29158916, 2017). "Importantly, further in vivo analyses suggest that paeoniflorin may protect against retinal ischemia by downregulating ischemia-related upstream β-catenin and downstream HIF-1α, VEGF, and Ang-2, with similar effects to Wnt/β-catenin inhibitor DKK1, anti-angiogenic PEDF, and anti-VEGF Avastin." (PMID 41303406, 2025).
lung squamous cell carcinoma (5 papers, 2021 to 2025). "DKK1 is overexpressed in various cancers (including lung squamous cell carcinoma) and is a putative biomarker for targeted therapy and a predictor for prognosis." (PMID 36409488, 2023).
mesothelioma (5 papers, 2010 to 2023). A usually malignant and aggressive neoplasm of the mesothelium which is often associated with exposure to asbestos. "It is consistent with previous findings that OE of DKK1 in both mesothelioma cell lines and zebrafish activates the non-canonical Wnt signaling pathway and higher phosphorylated JNK." (PMID 36410795, 2023). "Univariate and multivariate Cox analyses of DKK1 expression with overall survival (OS) among mesothelioma (MESO) patients." (PMID 34899842, 2021). "In mesothelioma cells DKK-1 activates the JNK pathway to induce apoptosis." (PMID 21317455, 2010). "By real time PCR we found that our cell cultures expressed high mRNA levels of typical mesothelioma markers as mesothelin (MSLN) and calretinin (CALB2), of BMI-1, a stemness marker and of DKK1, a potent Wingless [WNT] inhibitor." (PMID 20175889, 2010). "By real time PCR we found that our cell lines expressed high mRNA levels of typical mesothelioma markers as mesothelin (MSLN) and calretinin (CALB2), and of BMI-1, a stemness marker, and DKK1, a potent Wingless [WNT] inhibitor." (PMID 20175889, 2010). "MM cell cultures expressed high mRNA levels of the mesothelioma markers mesothelin (MSLN), calretinin (CALB2), the WNT1 antagonist DKK1 and the stem cell marker BMI-1." (PMID 20175889, 2010).
rheumatic diseases (5 papers, 2012 to 2025). "Previous studies have linked variation in the expression of DKK1 by synovial fibroblasts to rheumatic diseases associated with excessive bone formation, primarily AS although abnormal expression of the osteocyte-specific protein (and Wnt signalling inhibitor) sclerostin has also been described." (PMID 23079210, 2012). "In postmenopausal patients without rheumatic disease, discrepant results of the relationship between DKK-1 and BMD were also observed." (PMID 34497849, 2021).
sclerosteosis (5 papers, 2012 to 2023). "However, studies have shown that in order to compensate for the loss of sclerostin in sclerosteosis and Van Buchem disease patients, as well as in Sost KO mice, expression of other Wnt inhibitors such as Dickkopf-related protein 1 (DKK1) are upregulated." (PMID 32366042, 2020). "DKK1 levels are significantly higher in patients with both sclerosteosis and van Buchem disease (VBD) when compared to levels in carriers of the two diseases (sclerosteosis) and healthy controls." (PMID 36768718, 2023). "Sclerosteosis and van Buchem disease present with increased levels of DKK1 in sera." (PMID 31698687, 2019).
adenoma (4 papers, 2008 to 2024). A neoplasm arising from the epithelium. "Serum DKK1 level was significantly higher in patients with advanced cancer and adenoma than in controls." (PMID 38334454, 2024). "Serum DKK1 level revealed area‐under‐the‐curve values of 0.78 and 0.64 for cancer and adenoma, respectively." (PMID 38334454, 2024). "Gene expression analysis of NFs after co‐culture showed that DKK1 was progressively upregulated in co‐culture with adenoma and cancer organoids." (PMID 38334454, 2024). "Next, we examined the expression of DKK-1 protein in adenomas and a cohort of 699 CRC patients with clinical follow-up." (PMID 25788273, 2015). "Moreover, serum DKK1 concentration before and after treatment in patients with advanced adenoma (n = 17) showed a decrease in the after‐treatment group compared with that in the before‐treatment group (p = 0.023); the AUC was 0.64." (PMID 38334454, 2024). "Furthermore, analysis of serum before and after treatment in patients with advanced adenomas showed a significant decrease in serum DKK1 levels after treatment." (PMID 38334454, 2024). "Moreover, serum DKK1 concentration before and after treatment in patients with advanced adenoma showed a decrease in the after‐treatment group compared with that in the before‐treatment group; the AUC was 0.64." (PMID 38334454, 2024). "Data quantification across the series revealed absence of nuclear DKK-1 in 22% of adenomas and 75% of carcinomas, and a loss of DKK-1 expression during tumor progression that occurred earlier in the nucleus than in the cytoplasm." (PMID 25788273, 2015). "As the objective was to evaluate the response in the early stages of tumor development, we evaluated the expression of DKK1 by IHC staining in 27 nonadvanced adenomas, 25 advanced adenomas, and 56 advanced cancer specimens." (PMID 38334454, 2024). "DKK1 was expressed predominantly in the tumor stroma in nonadvanced adenomas, with a trend toward predominant expression in the tumor adenoduct beginning in advanced adenomas." (PMID 38334454, 2024).